CD4 (CD4 molecule)
Diseases named in the same sentence as CD4 in open-access papers (continued):
Sharing a sentence is not in itself a finding about the gene and the disease.
HIV-1 infection (continued). "However, HIV-1 infection results in the progressive loss of CD4+ T cell responses, which is characterized as both a decline in the number of CD4+ T cells and a loss of the functional activity of cells with certain antigenic specificities." (PMID 21752277, 2011). "Thus, depending on the in vitro stimulation of CD4+ T cells, the susceptibility to R5 and X4 HIV-1 infection can vary." (PMID 21284907, 2011). "A relentless destruction of CD4+ T cells represents another hallmark of HIV-1 infection." (PMID 21085612, 2010). "HIV-1 infection causes depletion of intestinal lamina propria CD4+ T cells (LPL), therefore, intestinal CD4+ T cell preservation may be a useful correlate of protection in evaluating vaccine candidates." (PMID 20085648, 2010). "Indeed, a dysfunctional HIV-1-specific CD4+ response is a hallmark of chronic HIV-1 infection, and adversely influences the development and functioning of the CD8+ T-cell response." (PMID 20613977, 2010). "During HIV-1 infection of CD4+ cells, SCMs compete for cell-associated CD4." (PMID 19343205, 2009). "According to the loss in CD4+ T-cells during primary SIV/HIV-1 infection and the infiltration of cytotoxic CD8+ T-cells within the GC of various lymphoid organs in chronically infected individuals, we stained sections from spleen (data not shown) and MLN on D28 p.i. for CD3, CD4, CD8 and CD45RO." (PMID 19543531, 2009). "Importantly, we have previously shown that in HIV-2 infected patients, as in HIV-1 infection, CD4 depletion is directly linked to immune activation." (PMID 19936055, 2009). "On the contrary, prior to administration of HAART in chronically infected patients, HIV-1 infection is associated with a failure in T cell homeostasis, resulting in a gradual decline in CD4+ T cell numbers (red line panel b), whereas the cytotoxic activity is well developed (red line in panel c)." (PMID 19840392, 2009). "Other studies have shown that the loss of CD8+ T cell responses in HIV-1 infection could be reversed by vaccine-induced CD4+ Th cell responses." (PMID 19555490, 2009). "In immunocompetent individuals, the parasite persists in the CNS as an asymptomatic chronic infection; however, in the presence of an HIV-1 infection, and the subsequent decrease in CD4+ cells, the T. gondii infection can reactivate and cause a disease known as Toxoplasma encephalitis." (PMID 19674458, 2009). "In addition, the naïve CD8+ T-cell population has also been shown to be the most susceptible to HIV-1 infection following activation-induced up-regulation of the CD4 cell-surface molecule by antibodies to CD3 and CD28." (PMID 18923697, 2008). "Previous studies implicated resting and activated CD4+ T cells, while others concluded that Langerhans cells (LC), dendritic cells, and macrophages were the likely first targets of HIV-1 infection in the human lower reproductive tract." (PMID 17306567, 2007). "The association of HSV-2 with higher susceptibility to HIV-1 infection may be attributable to higher CD4+ T cell counts in circulation and in turn with higher target cell availability for HIV-1 in sites of entry." (PMID 17957262, 2007). "In addition, we extended previous work on the in vitro susceptibility of purified donor CD4 T cells (n = 125) to HIV-1 infection, and on the susceptibility of HeLa cells that were stably transduced with the different TRIM5 variants." (PMID 16925802, 2006). "Together, these results raised a question whether CD4 down-modulation in vivo is a significant cause of SIR in HIV-1 infection." (PMID 16107223, 2005). "However, CD4+ T cell loss rate was in the same range as what has been described after treatment interruption in chronic HIV-1 infection." (PMID 15526059, 2004). "In addition to facilitating ADCC responses, CD4 mimetic compounds may reduce CD4+ T cell loss during HIV-1 infection." (PMID 41583464, 2025).
HIV-1 infection (continued). "Indeed, in addition to autophagy allowing energy-dependent IL-21 production and cell polyfunctionality in HIV-1-specific CD4 T-cells, it is now clear that glutaminolysis-dependent energy production also increases T-cell susceptibility to de novo HIV-1 infection." (PMID 37446195, 2023). "The precise mechanisms underlying CD4 T cell depletion in acute HIV-1 infection remain unknown." (PMID 36000842, 2022). "Interestingly, productive HIV-1 infection of these vaginal CD4+ TRM cells was linked to the activation of uninfected bystander CD4+ T cells, which may amplify and facilitate the dissemination of the viral infection." (PMID 35488095, 2022). "HIV-1 infection leads to a progressive loss of CD4+ T cells, which may be due to the viral cytopathic effect in productively infected CD4+ T cells and the bystander effect in uninfected CD4+ T cells." (PMID 34987521, 2021). "Importantly, unique broadly neutralizing antibodies (bnAbs) can naturally evolve in some HIV-infected people, with the ability to hinder HIV-1 infection by selectively targeting vulnerable sites on the viral envelope protein that mediates virus entry into susceptible CD4+ T cells." (PMID 34122453, 2021). "Therefore, the immunosuppression caused by the chronic HIV-1 infection itself, leading to a progressive loss of CD4+ T lymphocytes, might prevent the development of MS in HIV-1 infected subjects." (PMID 34795677, 2021). "Thus, CMV-specific CD4+ T cells are less susceptible to HIV-1 infection and are preserved." (PMID 31910871, 2020). "Thus, taken together, Meth treatment can elevate the expression of miRs-34c-5p and 155 which have been shown to increase CD4+ T-cell activation, and may make the cells more susceptible to HIV-1 infection." (PMID 30700725, 2019). "Thus, the different kinetics of CD4 T cell loss may be due to antigen-specific T cell responses against HIV-1 infection releasing IFN-γ." (PMID 30867315, 2019). "Although it can be hypothesized that antigen-specific CD4+ cell activation may also generate new targets for HIV-1 infection, the risk of propagating productive infection is largely counterbalanced by CIITA expression, as a potent HIV-1 restriction factor, strongly inhibiting virus replication." (PMID 29385169, 2018). "Our results indicate that CD4+ T cell counts in the genital mucosa are the greatest determinant of HIV-1 infection risk, meaning higher CD4+ T cell counts due to other STIs may have kept CD4+ T cell counts too high for significant reductions in HIV-1 infection risk." (PMID 29698393, 2018). "The depletion of CD4+ T cells associated with HIV-1 infection is thought to play a major role in the increased risk of TB and its extra-pulmonary dissemination in infected individuals, asM.tb infected macrophages require CD4+ T cells to augment intracellular clearance." (PMID 30210785, 2018). "Moreover, abortive HIV-1 infection of tissue CD4+ T cells has been implicated in pyroptotic cell death, which might directly promote pro-inflammatory programs in phagocytes." (PMID 29312342, 2017). "Consequently, the susceptibility of CD4+ T-cell subpopulations to HIV-1 infection, in addition to their mean half-life and homeostatic proliferation, is a key factor in the contribution of each subset to viral persistence in long-term virologically suppressed patients." (PMID 27484989, 2016). "Both viruses can use CCR5 as a coreceptor and target CD4+ cells such as T-lymphocytes and macrophages, resulting in the complete loss of these cells but the disease course in macaques infected with SIVmac is short relative to that of HIV-1 infections (1–3 years versus 6–10 years)." (PMID 27906032, 2016). "In addition, TGFβ may increase the expression of CCR5 and CXCR4, thereby increasing the susceptibility of CD4+ T cells to HIV-1 infection." (PMID 25802474, 2015).
HIV-1 infection (continued). "The results suggested that CD4+ T cells from the elderly are highly susceptible to HIV-1 infection but may show reduced virus production rates due to high levels of apoptosis that might be associated with a shortened average life span of virally infected T cells compared to young individuals." (PMID 26452480, 2015). "Indeed correlations between CD4+ T cell count and mir-31 and mir-150 during HIV-1 infection have been observed previously, albeit in cell associated miRNAs derived from PBMCs rather than in serum as we observed here, providing support for the validity of the results observed here." (PMID 26465293, 2015). "Besides direct killing of HIV-1 infected CD4 cells, bystander cells including hematopoietic progenitor cells and uninfected human mature cells are also depleted, associated with immune hyperactivation during pathogenic HIV-1 infection." (PMID 25077616, 2014). "For example, HIV-specific CD4+ T cells induced by the Step vaccine may have preferentially served as susceptible target cells for HIV-1 infection, or pre-existing Ad5-specific immunity could have played a role in HIV-specific immune responses and risk of HIV-1 infection." (PMID 25369172, 2014). "A second report found that macrophages from EC have low susceptibility to HIV-1 infection, while CD4 T-cells from the same patients, had reduced reverse transcription in the first round of infection, similar to the first report, although no direct role for p21 could be found." (PMID 23630526, 2013). "Although CD4 cells are lost, loss rates are orders of magnitude less than everyday turnover, such that typical depletion rates represent a mismatch between proliferation and death of only ∼1%; hence even in progressive HIV-1 infection, at least 99% of dying lymphocytes are replaced on a daily basis." (PMID 23637601, 2013). "Therefore, as for HCV infection, SIL may modulate fundamental metabolic processes that result in the blunting of multiple cellular responses including activation and proliferation, which ultimately renders CD4+ T cells less susceptible to HIV-1 infection." (PMID 22848626, 2012). "Potential mechanisms need investigation, including whether the male genital microbiota, in particular anaerobes, are associated with urethral and penile inflammation and activation of Langerhans cells and CD4+ T-cells, which could increase risk of HIV-1 infection in men." (PMID 22745608, 2012). "Moreover, P. marneffei -stimulated DCs could further activate resting CD4+ T cells to induce more susceptible targets for HIV-1 infection." (PMID 22110688, 2011). "HIV-1 infection causes a generalized state of immune dysfunction characterized by simultaneous chronic immune activation associated with a paradoxical anergy in both CD4+ and CD8+ T cell compartments resulting in increased susceptibility to opportunistic infections and malignancy." (PMID 21994747, 2011). "Indeed, loss of cell surface CD4 is a hallmark of HIV-1 infection." (PMID 18267010, 2008). "Hence, the same viral co-infection which may increase susceptibility to HIV-1 infection due to chronic mucosal tissue inflammation and or ulceration may in turn be associated with higher CD4+ T cell counts after acquisition of HIV-1." (PMID 17957262, 2007). "Our findings suggest that associations between lower serum selenium, lower CD4 count, and higher plasma viral load may be related to the frequent occurrence of low serum albumin and the acute phase response among individuals with more advanced HIV-1 infection." (PMID 16712720, 2006). "The same patterns of in vitro CD4 T cell resistance to HIV-1 infection were observed after alleged interruption of at-risk behaviors, suggesting that the mechanisms of resistance in these subjects do not depend on exposure to the virus but rather might be linked to constitutive factors." (PMID 17092330, 2006).
HIV-1 infection (continued). "In accordance with our data from A549 cells, although of a more limited magnitude, these results show that 3’ UTR shortening events induced by HIV-1 infection of primary CD4+ T cells correlate with the interaction between the viral capsid and CPSF6." (PMID 41405390, 2026). "CD4+ T Cells: HIV-1 infection dramatically reprograms CD4+ T cell metabolism, upregulating nearly all branches of metabolism, including glucose, lipid, and amino acid metabolism, to fuel its own replication." (PMID 41601636, 2026). "Exogenous M-CSF is capable of rendering macrophages more susceptible to HIV-1 infection, most likely through its ability to enhance expression of the HIV-1 receptor and co-receptor (CD4 and CCR5, respectively)." (PMID 40507836, 2025). "Based on these findings, the authors suggested a model of CD4+ T cell depletion in HIV-1 infection in which the suppression of PI3K/ATM promotes telomeric DNA damage and erosion." (PMID 40244051, 2025). "Polysome profiling revealed that PLIN3 mRNA was less actively translated during HIV-1 infection of primary CD4+ T cells." (PMID 41085277, 2025). "The CD4+ T-cell depletion that occurs in HIV-1 infection largely results from bystander death, an effect that has been attributed to Vpr release from infected cells and uptake by neighboring cells." (PMID 40901928, 2025). "In summary, we identified m6A modification sites at single-base resolution on viral and cellular RNA that occur in response to HIV-1 infection of primary CD4+ T cells." (PMID 41085277, 2025). "Our m6A-SAC-seq analysis revealed that the relative abundance of m6A changed significantly at three sites upon HIV-1 infection of primary CD4+ T cells." (PMID 41085277, 2025). "The overexpression of MiR-132 enhanced the replication of HIV-1 and rendered activated CD4+ T cells more prone to HIV-1 infection." (PMID 40296890, 2025). "Although the function of Vpr in HIV-1 infection and replication in macrophages is relatively well-characterized, the role of Vpr in CD4+ T cells is less well understood." (PMID 40901928, 2025). "Upon HIV-1 infection, the clinical condition begins when there is rapid and mass depletion of CD4+ T cells as they serve as primary target cells of HIV-1 due to the availability of C-C chemokine receptor type 5 (CCR5) co-receptors." (PMID 40733607, 2025). "Next, to confirm the inhibitory effect of GJB2 on HIV-1 infection in stimulated CD4+ T cells, we infected stimulated CD4+ T cells with VSV-G-pseudotyped HIV-1." (PMID 40980890, 2025). "In response to early HIV-1 infection, various host immune responses are triggered, contingent upon the subtype of CD4+ T cells." (PMID 40838493, 2025). "In our study, chronic HIV-1 infection is characterized by persistent viral replication, CD4+ T cell depletion, and increased immune activation, all of which worsen without treatment." (PMID 40333129, 2025). "The hallmarks of HIV-1 infection in humans (e.g. peripheral viral load and human CD4 + T-cell decline), are reflected in these humanized mice." (PMID 40630517, 2025). "We established an unbiased, phenotypic flow cytometry–based screen using an arrayed panel of 332 antibodies to identify receptors on the surface of primary CD4+ T cells, which are specifically modulated upon HIV-1 infection." (PMID 40911682, 2025). "NEAT1 is a well-known lncRNA and is identified as an antiviral in an HIV-1 infection context; its knockdown promotes viral production in CD4+ T cells because NEAT1 sequesters gRNA in nuclear paraspeckles." (PMID 40429887, 2025). "We chose to focus further on m6A modification of PLIN3 mRNA during HIV-1 infection of primary CD4+ T cells." (PMID 41085277, 2025). "In future work, we plan to expand the investigation of redox in HIV-1 infection with CD4-independent Env isolates and CD4 mutants with fixed isomerization states." (PMID 39912667, 2025).
HIV-1 infection (continued). "TGF-β signaling is also shown to promote CCR5- tropic HIV-1 infection in resting and activated memory CD4+ T cells in SMAD3- dependent manner and blockade of TGF-β was shown to drive transitional effector phenotype in T cells." (PMID 40632811, 2025). "The initial step of HIV-1 infection involves the virus attaching to its specific receptor CD4, and co-receptors CCR5, or CXCR4 on host immune cells." (PMID 40586616, 2025). "Anti-Tat antibodies have been shown to correlate with markers of disease progression such as CD4+ T-cell count and viral loads in chronic HIV-1 infection." (PMID 40607402, 2025). "It is known that HIV-1 infection of macrophages is slowed by naturally reduced endogenous dNTP pools relative to higher dNTP pools in activated CD4 T cells and transformed tissue culture models." (PMID 40586616, 2025). "It has been established that untreated HIV-1 infection primarily targets and damages CD4+ central memory T cells." (PMID 40061947, 2025). "HIV-1 infection targets CD4 + T cells and leads to their depletion via both direct and indirect mechanisms." (PMID 40779581, 2025). "Compared with those in HIV-1 progressors and HIV-1-negative individuals, CD4+ T cells from ECs are less sensitive to HIV-1 infection." (PMID 40070826, 2025). "Accumulating evidence, including our prior work, has established that sustained IFN-I signaling during chronic HIV-1 infection exacerbates CD4+ T cell depletion, impairs adaptive immunity, and promotes viral persistence." (PMID 40872811, 2025). "Arp3 (ACTR3) is necessary for HIV-1 env-mediated cell–cell fusion, virus–cell fusion, and HIV-1 infection in U87 cells expressing CD4 and CCR5." (PMID 41226631, 2025). "The frequency of CD4+ Tregs was elevated following HIV-1 infection compared to HIV-seronegative individuals, except, notably, in the case of the HLTBI+ group." (PMID 41148837, 2025). "While VSV-G mediates entry through receptor-mediated endocytosis, bypassing the physiological CD4/co-receptor pathway, this approach enabled us to overcome natural entry barriers and directly model the intracellular impact of productive HIV-1 infection." (PMID 40420159, 2025). "Future studies will focus on the role of PLIN3 in HIV-1 Env incorporation to better understand how PLIN3 regulates HIV-1 infection in primary CD4+ T cells." (PMID 41085277, 2025). "CD4+ T lymphocytes are the main target cells of HIV-1 infection, and their count serves as a crucial indicator of HIV progression." (PMID 40331958, 2025). "Other A3 proteins, including A3C-I188, A3D, A3F, and stable haplotypes of A3H, also restrict HIV-1 infection in CD4+ T lymphocytes." (PMID 40004025, 2025). "Next, the ability of Vpu to down-regulate CD96 was analyzed in the context of HIV-1 infection and compared to other established Vpu functions such as the down-regulation of CD4 and CD317 (Tetherin)." (PMID 40911682, 2025). "Although myeloid cells are more resistant to HIV-1 infection than CD4+ T cells, some cytokines, including interleukin (IL)-4 and IL-6, promote myeloid cell infection." (PMID 40980890, 2025). "For instance, HIV-1 infection has been reported to downregulate CD4 expression, likely through the HIV-1 virulence factor nef." (PMID 40970711, 2025). "The gut-associated lymphoid tissues (GALTs) represent the primary location for CD4+ T-cell depletion during the acute phase of HIV-1 infection and also constitute an important site for HIV-1 reservoir persistence during the chronic phase." (PMID 41227377, 2025). "We found that HIV-1 infection of primary CD4+ T cells promotes the interaction between the m6A writer complex subunits that add m6A modification." (PMID 41085277, 2025). "For the purposes of the current study, we chose to focus on transcripts that become significantly hypermethylated in primary CD4+ T cells upon HIV-1 infection compared with mock-infected controls." (PMID 41085277, 2025).